ORAI1 (ORAI calcium release-activated calcium modulator 1)
Diseases named in the same sentence as ORAI1 in open-access papers (continued):
Sharing a sentence is not in itself a finding about the gene and the disease.
tumor (continued). "Functional assays revealed that mCRC cell proliferation and migration are not affected in Stim1-, Orai1- and Orai3-deficient cells, thereby confirming that Stim and Orai proteins do not mediate tumor growth and metastases in patients-derived CRC cells." (PMID 30123430, 2018). "Moreover, SOCE was inhibited by BTP2 and 10 μM La3+, which block SOCs contributed by Orai1 and TRPC1 in a growing number of cell types, including tumor-associated ECFCs." (PMID 29221123, 2017). "Signaling of tumor-cells may further involve up-regulation of pore forming Ca2+ channel protein Orai1, which accomplishes store operated Ca2+ entry (SOCE)." (PMID 26690689, 2015). "The Ca2+ channel units Orai1, 2, or 3 and their regulators STIM 1 or 2 have been implicated in the resistance to apoptosis, in proliferation, and in migration of tumor cells." (PMID 25015419, 2014). "Through Fluo-4–based intracellular Ca2+ measurement, we found that downregulation of Orai1 did reduce the amplitude of Ca2+ influx in tumor cells, but re-expression of the Orai1 construct could rescue the loss of Ca2+ influx." (PMID 25433371, 2014). "Curiously, a recent investigation conducted on primary cultures established from GBM disclosed that Stim1/Orai1 account for ~20% of cell growth, thereby confirming that freshly isolated tumour cells may become independent on SOCE to proliferate." (PMID 25126575, 2014). "Orai1/STIM1 complex is implicated in breast, nasopharyngeal carcinoma, cervical and glioblastoma multiforme tumor cell migration in vitro and in a mouse model of metastases generated by tumor xenografts." (PMID 24204345, 2013). "The sustained Ca2+ release required for the nuclear translocation of NFAT and its subsequent regulation of FasL expression lends support to the theory that intact SOCE as regulated by STIM1, STIM2, Orai1 can have transcriptional effects that affect the function of cytotoxic T cells against tumours." (PMID 24000152, 2013). "Specifically, the ALDHhigh CSC population expressed more ORAI1 proteins, and a study showed that ectopic expression of ORAI1 in nontumorigenic immortalized oral epithelial cells resulted in increased proliferation, self-renewal, and tumor-initiating capacities." (PMID 35628366, 2022). "Moreover, both tumor cell migrations were also blunted by silencing ORAI1." (PMID 33386992, 2021). "Our results demonstrate that RAC1 controls ORAI1 localization at the leading edge where this channel regulates lamellipodia formation, lamellipodial persistence, and cell directness, which are required for efficient cell migration and tumor cell invasiveness in vivo." (PMID 32313105, 2020). "Thus, the down-expression of STIM1 or Orai1 could impair cell migration and/or intralymphatic spread, promoting homing of tumor B cells to extra-nodal sites." (PMID 30373149, 2018). "Silencing the ORAI1 channel in tumor cells inhibits the secretion of PD-L1 exosomes, increases CD8+ cells, and impedes tumor progression." (PMID 40475777, 2025). "Phemindole treatment reduces STIM1 expression by reducing the interaction between STIM1 and Orai1, resulting in decreased cell migration in vitro through the regulation of FAK; a reduction in tumor growth in vivo was also observed." (PMID 36982380, 2023). "Specifically, polyamine synthesis inhibition decreased the expression of the TRPV6 and TRPP1 channels, as well as the Orai1 positive modulator SPCA2, probably contributing to decreased Ca2+ influx in DFMO-treated tumor cells." (PMID 36900391, 2023). "To investigate the expression of ORAI1 in human CRC tissues, we first examined ORAI1 expression in 80 CRC tissue samples and non-tumor tissues by immunohistochemical staining (IHC)." (PMID 34055617, 2021). "Being involved in store-operated calcium entry, both ORAI1 and STIM1, are essential for breast tumor cell migration and tumor metastasis." (PMID 34988012, 2021).
tumor (continued). "We further detected ORAI1 expression in an additional 40 fresh CRC tissues and the corresponding non-tumor tissues by Western blot analysis." (PMID 34055617, 2021). "Similar to Orai1, TRPC6 is also overexpressed in ESCC tumor tissues compared with normal esophageal tissues in terms of both mRNA and protein levels and its high expression is associated with poor prognosis." (PMID 34012400, 2021). "It was also used in our early work in ESCC and was demonstrated to decrease Orai1-mediated SOCE and to reduce tumor growth in vivo." (PMID 34012400, 2021). "Not only the main players of SOCE, STIM1 and Orai1, but also the slightly “neglected” STIM2 and Orai3 are involved in proliferation and growth of tumor cells." (PMID 30935064, 2019). "We performed qRT-PCR, intracellular Ca2+ monitoring, protein analyses, and real-time cell proliferation assays on EpCAM(+)CD133(+) subpopulation of tumor-initiating Huh-7 HCC cells expressing high levels of STIM1 and/or Orai1." (PMID 31366337, 2019). "Herein, we provided the evidence that Stim1-2, Orai1 and Orai3 proteins mediate constitutive Ca2+ entry in both primary and metastatic CRC cells deriving from human tumor samples." (PMID 30123430, 2018). "The migration and the invasion processes of tumor cells can be regulated by many factors, such as BRMS1, E-cadherin, CXCL12, MMP9, Orai1, Stim1, TGF-β, and VEGF." (PMID 29316690, 2018). "Tumor volume at the end of day 39 in mice injected with high salt passaged MCF-7s cells was 483 ± 64 mm3; while tumor volume in mice injected by Orai1-KO-MCF-7s cells on day 39 was 316 ± 72 mm3 (p < 0.05)." (PMID 29861863, 2018). "Therefore, Stim1 and Orai1 may be also activated in resting, i.e. not stimulated, tumor- and tumor-associated cells, thereby mediating a constitutive influx of Ca2+." (PMID 30123430, 2018). "The composite molecules of SOCE; i.e., Orai1 and STIM1 suggest a poor outcome for GC by advancing tumor cell proliferation, metabolism, migration, and invasion through targeting metastasis-associated in colon cancer-1 (MACC1)." (PMID 28264681, 2017). "Effect of Orai1 inactivation on tumorigenic potential of OSCC was then evaluated using in vitro anchorage independent growth and in vivo tumor xenograft assay." (PMID 27259269, 2016). "Orai1 is highly expressed in CSC-enriched cell populations, such as tumor spheres and ALDH1HIGH population of OSCC." (PMID 27259269, 2016). "The role of ORAI1/STIM1 complex has been studied recently also in EC migration and tumor vascularization." (PMID 24204345, 2013). "Resting Ca2+ levels were significantly lowered in both SPCA2 and Orai1 knockdown cells, consistent with our previous observation in HEK293 and tumor-derived MCF7 cells." (PMID 23840669, 2013). "In this view, Stim1, Orai1, and TRPC1 stand out as very promising molecular identities to hit to adverse tumor neovascularization." (PMID 23049731, 2012). "In several neoplasms, ORAI3 appears to supersede ORAI1 in functional relevance." (PMID 41596760, 2026). "Furthermore, our findings are consistent with prior studies showing that SOCE components, such as STIM1 and Orai1, are upregulated in HCC and promote tumor progression." (PMID 40362663, 2025). "Thus, our findings support a model whereby EHD2-dependent stabilization of cell surface caveolae ensures high cell surface levels of Orai1 to enable robust SOCE in TNBCs, which in turn promotes pro-tumorigenic and pro-metastatic behaviors of tumor cells." (PMID 36625722, 2023). "They found that miR-519 inhibits the growth and survival of tumor cells via repressing the expression of proteins involved in DNA maintenance (including DUT1, EXO1, RPA2, and POLE4) and intracellular calcium homeostasis (ATP2C1 and ORAI1)." (PMID 37601663, 2023). "Decreased Orai1-mediated SOCE, either by gene knockdown or pharmacological channel blockers, is able to reduce the frequency of intracellular Ca2+ oscillations in cultured ESCC cells and to inhibit tumor growth in preclinical animal models." (PMID 35163685, 2022).
tumor (continued). "In addition, transcriptomic analysis of glioblastoma tumor tissues showed overexpression of STIM1, ORAI1, and TRPC1." (PMID 35711942, 2022). "On the other hand, the ectopic expression of ORAI1 in non-tumorigenic immortalized oral epithelial cells increased proliferation, self-renewal, and tumor-promoting capacities, implying the functional importance of Orai1/NFAT axis in OSCC CSC regulation." (PMID 36142596, 2022). "In several tumor types, enhanced proliferation correlates with ectopic STIM1/Orai1 expression." (PMID 36612099, 2022). "We previously reported upregulated expression of Orai1 in tumor tissues compared to that in adjacent non-tumorous tissues in ESCC patients." (PMID 34012400, 2021). "But there were no statistical connections between ORAI1 overexpression and age, gender, and tumor size." (PMID 34055617, 2021). "The most extensively examined molecules of SOCE in tumor biology are STIM1 and Orai1." (PMID 31252656, 2019). "Moreover, the expression of TRPC1, ORAI1, ORAI2, ORAI3 and STIM1 was increased in tumor cells in contrary to STIM2 protein which was found to be depleted." (PMID 31010205, 2019). "Furthermore, the high Orai1 and STIM2 expression found in melanoma biopsies at the rim of invading tumors are linking their possible role in tumor invasion and/or metastasis in vivo." (PMID 30935064, 2019). "We demonstrated that targeting HSP27 selectively affects STIM1, which regulates and coordinates Ca2+ entry into the tumor cells, but not Orai1." (PMID 30544747, 2018). "Orai1 and STIM1 have been shown to be highly expressed in tumor cells, and may contribute to malignant biological behaviors." (PMID 28264681, 2017). "In addition, Orai1 and STIM1 are crucial for breast cancer cell migration in vitro and tumor metastasis in vivo." (PMID 28264681, 2017). "The invasion of tumor cells could be regulated by many factors such as BRMS1, E-cadherin, Keratin19, LOXL2, MMP9, Orai1, Stim1, TGF-β and VEGF." (PMID 27008697, 2016). "Orai1 and STIM1 are expressed in tumor cells and may well contribute to the survival of therapy resistant cells." (PMID 25015419, 2014). "Moreover, pharmacologic inhibition of Orai1 activity or reduction of Orai1 expression suppressed proliferation and migration of ESCC in vitro and slowed tumor formation and growth in in vivo xenografted mice." (PMID 24797725, 2014). "An unexpected finding in the present study was the observed increase in Orai1 expression with no increase in STIM1 expression in ESCC tumor tissues." (PMID 24797725, 2014). "In fact, Orai1 is overexpressed in some tumors, and downregulation of both STIM1 and Orai1 by siRNA or directly blocking store-operated Ca2+ entry with the drug SKF96365 (1-[2-(4-methoxyphenyl)-2-[3-(4-methoxyphenyl)propoxy]ethyl]imidazole) inhibited tumor cell migration and metastasis development." (PMID 31991573, 2020). "Thus, the inhibition of Ca2+ entry through Orai1 and Orai2 channels by slightly increased ROS in the TME may increase immune cell cytotoxicity against a tumor." (PMID 30935064, 2019). "Similar to RCC-ECFCs, however, the pharmacological inhibition of SOCE abrogated BC-ECFC proliferation and tube formation, thereby confirming that Orai1 and TRPC1 could serve as reliable targets to interfere with tumor vascularization, although this hypothesis remains to be validated in vivo." (PMID 29324706, 2018). "Therefore, targeting a Ca2+ entry/release pathway tightly coupled to either eNOS (i.e., Orai1,) or CSE (yet to be identified) has the potential to interfere with multiple pro-angiogenic pathways and, therefore, exert a more profound anti-tumor effect." (PMID 29324706, 2018). "In the same study, we also showed that inhibition of Orai1-mediated SOCE by pharmacologic antagonists of the channel or reduction of Orai1 expression by Orai1 knockdown impeded the proliferation and migration/invasion of ESCC cells in vitro, suppressed the tumor growth in vivo." (PMID 25481035, 2015).
tumor (continued). "The role of ORAI1 at the leading edge was studied in genetically engineered U2OS cells lacking ORAI1 expression that helped us to prove the key role of this Ca2+ channel on lamellipodia formation, lamellipodial persistence, and cell directness, which are required for tumor cell invasiveness in vivo." (PMID 32313105, 2020). "However, this ratio should not undermine the pro-tumor role of ORAI1." (PMID 31010205, 2019). "Compared to quiescent non-tumor cells, we identified a striking hyperactivity in Ca2+ oscillations in ESCC cells, which is dependent on Orai1-mediated SOCE since these oscillations could be suppressed by reduction of Orai1 function using either pharmacologic or molecular approaches." (PMID 25481035, 2015). "In non-tumor sections these proteins are either not expressed (DDR1 and SPCA2) or faintly expressed (Orai1 and Kv10.1), suggesting the importance of their simultaneous expression to sustain the aggressiveness and the resistance of the tumor." (PMID 30718673, 2019). "To determine the role of Orai1 on CSC phenotype of OSCC, we first employed tumor sphere formation assay in which CSCs can be enriched in non-adherent tumor spheres." (PMID 27259269, 2016). "In our study, we found an increased expression of Orai1 and STIM2 but not STIM1 in ESCC tumor tissues." (PMID 25481035, 2015). "This is in contrast to impaired cytolytic function of human NK cells lacking functional ORAI1, the pore-forming subunit of the CRAC channel, which had a severe defect in killing L1210 and K562 tumour cells." (PMID 23922331, 2013). "Interestingly, although the genes individually did not correlate with tumor progression, the ORAI3/ORAI1 Ratio was significantly increased in stages III and IV compared to Stage I in both TCGA and GSE39582 datasets." (PMID 31010205, 2019). "Likewise, Orai1 protein was largely expressed in primary CRC samples, but not in adjacent non-tumor tissues." (PMID 30123430, 2018).
myopathy (20 papers, 2011 to 2026). A disease of the muscle in which the muscle fibers do not function properly. "Patients with the G98S mutation in ORAI1 exhibit primarily skeletal muscle manifestations, including myopathy, exercise intolerance, and a robust presence of TAs upon electron microscopy (EM) analysis of muscle biopsies." (PMID 39420094, 2024). "Gain-of-function mutations in STIM1 and ORAI1 are linked to tubular aggregate (TA) myopathy, a disease characterized by the atypical accumulation of tubes of SR origin." (PMID 39200116, 2024). "Abnormal N-linked glycosylation of STIM1 and Orai1 has been observed in a variety of pathologies, including myopathies with tubular aggregates or septic myocardial depression." (PMID 36612199, 2022). "This has been hypothesized as ORAI1 hypo-glycosylation has been linked to the development of tubular aggregate myopathy and in limb–girdle CMS patients harboring mutation to DPAGT1." (PMID 39456185, 2024). "This indicates that incorporation of WT ORAI1 subunits markedly limits the degree of constitutive Ca2+ entry resulting from the G100S mutation, which likely explains the embryonic lethal phenotype of homozygous Orai1G100S/G100S mice and survival with a slowly progressive myopathy of GS mice." (PMID 39420094, 2024). "Therefore, our results may shed further light on the disease of myopathy caused by the L138F mutation in human Orai1, by providing insight into the detailed structure and activation mechanism of the L210F mutant." (PMID 34796201, 2021). "However, this diagnosis should be considered in patients presenting proximal dominant leg weakness, which may be confused with other types of muscular dystrophy or inflammatory myopathy in most cases of STIM1 or ORAI1 mutations." (PMID 27879676, 2016). "TAM was originally described as a myopathy associated with gain of function mutations in STIM1 and ORAI1, the two key proteins participating in the SOCE mechanism." (PMID 39126637, 2024). "These nonimmunological effects, also observed in an unrelated R2524C patient, partially overlap with the dental enamel formation defects and myopathy in ORAI1 and STIM1 patients, although the latter phenotypes are congenital and nonprogressive." (PMID 36302985, 2023). "Accordingly, these data suggest that RYR1 should be considered for genetic analysis in a myopathy with TA where STIM1, ORAI1 and CASQ1 mutations have been excluded." (PMID 35666680, 2022). "A significant amount of dysfunctional STIM1 and ORAI1 was accumulated in TAs, representing peculiar assembly of SR tubes; this was found in ageing and in several myopathies." (PMID 34201319, 2021). "In addition, a novel pathway was implicated in myopathies with the discovery of pathogenic variants in STIM1, ORAI1, and CASQ1 that are key players of Ca2+ homeostasis through the SOCE mechanism." (PMID 38982518, 2024). "Involvement of SOCE in genetic skeletal muscle diseases has been proposed when a missense mutation (R91W) in the first transmembrane domain of Orai1 was found in patients suffering from severe combined immunodeficiency (SCID) and presenting myopathy, hypotonia and respiratory muscle weakness." (PMID 34685702, 2021). "Not only are they present in muscle biopsies from patients with mutations in proteins involved in the glycosylation pathway but are also implicated in myopathies resulting from STIM1 and ORAI1 mutations, and are present in muscle from Caveolin1−/− and Caveolin2−/− mice." (PMID 29905857, 2018). "Finally, we discuss the phenotypes and the pathomechanism of myopathies caused by mutations in the STIM1 and ORAI1 genes." (PMID 27879676, 2016). "In the meantime, previous experiments have also shown that the L138F mutation in human Orai1 yields a constitutively permeant channel that allows ion conduction in the absence of STIM1, and the constitutively active L138F mutant channel can cause severe myopathy." (PMID 34796201, 2021).
myopathy (continued). "Here, we report on the identification of causative dominant RYR1 variants in two patients with a history of myopathy characterized by the presence of tubular aggregates in muscle biopsy and negative for mutations in STIM11, ORAI1 and CASQ1." (PMID 35666680, 2022). "Previous studies showed that the L138F mutation in the human Orai1 creates a constitutively open channel independent of STIM, causing severe myopathy, but how the L138F mutation activates Orai1 is still unclear." (PMID 34796201, 2021).